STAT3 (signal transducer and activator of transcription 3)
Diseases named in the same sentence as STAT3 in open-access papers (continued):
Sharing a sentence is not in itself a finding about the gene and the disease.
melanoma (continued). "Since STAT-3 is known to be expressed in large quantities in different human tumors and cell line, we investigated the cellular expression levels of STAT-3 in melanoma cells exposed to various concentrations of SD." (PMID 22363217, 2012). "With a focus on developing potential therapies toward melanoma, both MITF and STAT3 have been implicated in neoplastic progression." (PMID 22316093, 2012). "The expression of phosphorylated STAT3 (p-STAT3) has been shown to be higher in melanoma metastasis to the central nervous system (CNS) relative to distant metastasis in the rest of the body (systemic)." (PMID 22488042, 2012). "Suppression of p-JAK2 and p-STAT3 by SOID-8 in melanoma cells was observed in a time-dependent manner." (PMID 23166634, 2012). "Similar to our prior studies in melanoma, curcumin pre-treatment required a much higher concentration to inhibit basal STAT3 phosphorylation and also reduced IFN-γ-induced pSTAT1." (PMID 22899991, 2012). "Interleukin-6 (IL-6) is a critical growth factor for melanoma cells, IL-6 can directly activate STAT3 phosphorylation through JAK family kinases." (PMID 23166634, 2012). "STAT3 is constitutively overexpressed in many different cancers; in melanoma, 81% of CNS metastases express activated STAT3." (PMID 22488042, 2012). "Our results indicate that the antitumor activity of SOID-8 is at least partially due to inhibition of JAK2/STAT3 signaling in melanoma cells." (PMID 23166634, 2012). "The parent compound, curcumin has been shown to inhibit phosphorylation of STAT3 in a variety of human cell lines including melanoma, pancreatic, and biliary cancer among others, albeit at higher concentrations." (PMID 22899991, 2012). "Recent data suggests that inhibition of the JAK/STAT3 pathway is a potential therapeutic approach for melanoma." (PMID 23166634, 2012). "Many of the studies that defined the role of STAT3 in oncogenesis were carried out in cancer cells and animal models of melanoma, and targeting STAT3 signaling in melanoma cells is an appealing strategy." (PMID 23166634, 2012). "In that study, cloned human melanoma cell lines with enforced upregulation of constitutive STAT3 or blockade of STAT3 activity were evaluated for their ability to metastasize to the brain in murine models." (PMID 22488042, 2012). "The present findings revealed that MDA-7/IL-24 treatment of melanoma cells activates phosphorylation of STAT3 and down-regulates interferon regulatory factor (IRF-1) whereas up-regulating IRF-2 expression, which reduces iNOS expression level." (PMID 22629368, 2012). "We and others have previously shown that the constitutive activation of STAT3 in melanoma cells determines the development of tumor immune tolerance and tumor progression." (PMID 21931823, 2011). "The present study has demonstrated that the FLLL32 small molecule can inhibit STAT3 signal transduction and induce caspase-dependent, pro-apoptotic effects against human melanoma cell lines and primary melanoma cultures at micromolar concentrations." (PMID 20576164, 2010). "Curcumin, 1,7-bis(4-hydroxy-3methoxyphenyl)-1,6-heptadien-3,5-dione, is one such candidate based on its chemopreventative and therapeutic properties in experimental models including melanoma and its ability to inhibit a variety of targets including STAT3." (PMID 20576164, 2010). "Another study investigating the role of Stat3 in immune evasion in human melanoma cells, has reported that Stat3 siRNA decreased the mRNA expression of IL-6, IL-10 and VEGF." (PMID 21122157, 2010). "This supports the fact that Src activated STAT3 signaling has a key role in the survival and growth of melanoma tumor cells." (PMID 20796316, 2010). "Our data indicate that FLLL32 can inhibit STAT3 phosphorylation and promote caspase-dependent apoptosis of human melanoma cells at concentrations 10-fold lower than curcumin." (PMID 20576164, 2010).
melanoma (continued). "By studying human melanoma cell lines obtained from surgical specimens in vitro, we found that STAT3 was constitutively activated at a substantially higher level in brain melanoma tissues." (PMID 24281074, 2010). "The STAT3 transcription factor promotes a metastatic phenotype and has been shown to be constitutively phosphorylated in human melanoma cell lines." (PMID 20398276, 2010). "The present results provide evidence that the FLLL32 curcumin analog represents a promising lead compound on which to base the further development of STAT3-specific inhibitors against melanoma." (PMID 20576164, 2010). "STAT3, which has been shown to play an important role in tumor cell proliferation and survival, and c-Src tyrosine kinase are activated in melanoma cell lines." (PMID 20796316, 2010). "Recent studies from our group and others have demonstrated that the presence of constitutively active STAT3 in melanoma cells is correlated with reduced responsiveness to cytokines which act via STAT1 signal transduction." (PMID 20576164, 2010). "Specifically, activated Stat3 regulates tumor invasion of melanoma cells by regulating the gene transcription of MMP-2." (PMID 20482858, 2010). "FLLL32 specifically reduced STAT3 phosphorylation at Tyr705 (pSTAT3) and induced apoptosis at micromolar amounts in human melanoma cell lines and primary melanoma cultures as determined by annexin V/propidium iodide staining and immunoblot analysis." (PMID 20576164, 2010). "The role of Stat3 in angiogenesis was first shown when VEGF was found to be a direct target of Stat3 in mouse melanoma cells and then confirmed by a study in a human pancreatic cancer system." (PMID 20482858, 2010). "We summarize the structure, glycosylation and regulation of CD24, then discuss its role in melanoma, supporting phenotypic plasticity, sustaining stem-like populations and promoting resistance to BRAF-targeted and cytotoxic therapies through SOX2/STAT3-linked programmes." (PMID 42126185, 2026). "To address the possible role of endogenous, physiological oncogenic GLI activity, we performed RNA-interference (RNAi)-mediated GLI1 inactivation in human BRAFV600E mutated melanoma cells (WM35) and treated the cells with IL6 [75 ng/mL] for 18 h to activate IDO1 expression via STAT3." (PMID 39962447, 2025). "Finally, pSTAT3 levels also strongly correlated with constitutive IκBζ expression in human melanoma samples, especially in immunotherapy-resistant patients, validating the IκBζ-dependent regulation of STAT3 activation in melanoma." (PMID 40562773, 2025). "STAT3 suppression triggers apoptosis, enhancing melanoma cell death." (PMID 40399946, 2025). "For example, activation of STAT3 in melanoma could up‐regulate MMP‐2 expression by directly binding to its promoter." (PMID 41425852, 2025). "Administration of cationic liposomal curcumin in combination with STAT3 siRNA resulted in decreased growth of B16-F10 mouse melanoma cells in culture and tumor reduction in C57BL/6 mice injected with B16-F10 cells when compared with the groups treated with the individual agents." (PMID 41463545, 2025). "Artesunate inhibits melanoma progression by suppressing the STAT3 signaling pathway." (PMID 40758729, 2025). "Indeed, treating NK-92MI cells with supernatant from CCNB1-overexpressing melanoma cells activated STAT3 signaling." (PMID 40430484, 2025). "Notably, IL-6 secreted by CCNB1-high melanoma cells not only maintains STAT3 activation within tumor cells but also enhances STAT3 signaling in NK-92MI cells, potentially exacerbating NK cell dysfunction." (PMID 40430484, 2025). "LbL-AuNP reduced STAT3 protein expression and induced apoptosis in melanoma cells." (PMID 40336019, 2025). "Furthermore, melanoma STAT3 activation (pSTAT3Tyr70) and IL-6 secretion following exposure to ceramides was significantly increased." (PMID 40280124, 2025).
melanoma (continued). "Other compounds like 2′-hydroxyflavanone, tangeretin, and obacunone exhibit anti-STAT3, anti-inflammatory, and antiproliferative effects, while alkaloids and terpenoids contribute to cytotoxicity in hepatocellular, cervical, and melanoma models via redox modulation." (PMID 41346617, 2025). "Also, it was shown that ILs play a crucial role in the pathogenesis of melanoma by driving inflammation and expanding MDSCs, with IL-1β and the downstream IL-6/STAT3 axis being key contributors to this process." (PMID 40636453, 2025). "Interestingly, in vitro and in vivo experiments have validated that DHA reduces the expression of IL-10 and IL-6 proteins in melanoma and inhibits the phosphorylation of STAT3 to induce mitochondrial apoptosis." (PMID 41160271, 2025). "Inhalation delivery, using nebulized liposomes to target metastatic lung lesions, could leverage OC’s anti-STAT3 effects observed in melanoma lung models." (PMID 40564985, 2025). "STAT3 activation promotes melanoma cell proliferation, invasiveness, and metastasis." (PMID 40001571, 2025). "Although increased STAT3 and NF-κB activity in IκBζ-expressing melanoma could explain the elevated expression of IL-6 and IL-1 cytokines, STAT3 and NF-κB inhibition was unable to recover IκBζ-mediated suppression of Cxcl9, Cxcl10, and Ccl5 in melanoma cells." (PMID 40562773, 2025). "Moreover, luteolin was also noticed to downregulate the expression of genes that are targeted by STAT3 as well as are involved in cell survival and invasion in melanoma cells." (PMID 38474604, 2024). "In BRAF mutant melanoma cells, the STAT3 pathway is directly activated by PI3K-AKT." (PMID 38534309, 2024). "STAT3 activation promotes melanoma proliferation, aggressiveness, and metastasis." (PMID 38822350, 2024). "The authors of other studies have reported that napabucasin, an inhibitor of STAT3, could eliminate the immunosuppressive ability of mouse MDSCs and human M-MDSCs, and improve the survival rate of mice carrying melanoma." (PMID 39609883, 2024). "The ability of UV to induce miRNA-21 overexpression in melanoma involves the ROS-mediated modulation of transcription factors such as the signal transducer and activator of transcription 3 (STAT3), activator protein 1 (AP-1), and NF-κB, which all have recognition sites on the miRNA-21 promoter." (PMID 39057064, 2024). "Moreover, STAT3 has been demonstrated to promote metastasis of melanoma cells, thereby linking the loss in differentiation with the induction of markers related to the EMT-like cell state transition." (PMID 39398277, 2024). "In addition, apigenin suppressed other metastasis-favorable molecules including MAPK in intestinal adenocarcinoma cells, AKT in OVCAR-3 ovarian cancer cells, and STAT3 in B16F10 melanoma cells, respectively." (PMID 38515580, 2024). "The simulations propose that IL-6 secreted by high-E2F1 melanoma cells is sufficient to trigger the activation of the IL-6/IL6R/STAT3 axis in CD4+ immune cells, which could also trigger secretion of other inflammatory factors." (PMID 39544930, 2024). "Likewise, KCNQ1OT1 hinders the function of CD8 + T cells through the miR-34a/STAT3/PD-L1 axis, thereby facilitating immune evasion by melanoma cells." (PMID 38462628, 2024). "Furthermore, Herrmann and co-workers have demonstrated that the CTLA4/Tyk2/STAT3 axis is critical to the proliferation and survival of B cells and thus leads to the immune suppression in melanoma and lymphoma." (PMID 38245798, 2024). "Consequently, our data show less phosphorylation of STAT3 but rather accumulation of the total protein of STAT3 in melanoma." (PMID 38705997, 2024). "MDSCs were also reported to promote immune evasion in melanoma cells by inhibiting T cell activity and macrophage-mediated phagocytosis and to confer stemness properties to tumor cells by activating the IL-6/STAT3 signaling pathway." (PMID 39199632, 2024).
melanoma (continued). "Invasive melanoma phenotype has been associated with the signaling of steroid receptor coactivator (SRC), focal adhesion kinase (FAK), and STAT3, which are activated by the upregulation of RTK, posing other sites of potential inhibitors in conjunction with MAPKi for this specific phenotype." (PMID 39534873, 2024). "The STAT3 transcription factor is crucial in melanoma and many other cancer types." (PMID 39534873, 2024). "We next sought to determine whether STAT3 signaling mediates BET inhibitor-induced sensitization of melanoma cells to sunitinib." (PMID 36720918, 2023). "Together, these findings demonstrate that the IFN-γ-induced PD-L1 expression in melanoma cells is negatively regulated by MET inhibition through the JAK/STAT3 signaling pathway and establish the colocalization and interaction between an RTK and a checkpoint protein in melanoma cells." (PMID 37444518, 2023). "To understand the mechanisms of the oncogenic activity of this mutant, we recently investigated potential non-canonical interactions in melanoma and found that in mouse melanoma cells, mutant Ezh2Y641F protein interacts directly with and methylates Stat3 protein." (PMID 37664059, 2023). "Consistent STAT3 activation in melanoma results from SRC and JAK activation." (PMID 36852795, 2023). "In vitro, the human melanoma cell line 1205Lu, stimulated with IL-1α, exhibited significantly lower levels of STAT3 Y705 phosphorylation by the combination treatment, thus affecting the nuclear functions of STAT3." (PMID 36672229, 2023). "In view of the fact that IL-6 influences the morphology, gene expression, and secretome of microglia, we hypothesized that melanoma-derived IL-6 binds to its receptor expressed by microglia cells to initiate a signaling cascade through the IL-6/STAT3 pathway." (PMID 37296634, 2023). "By blocking the JAK2/STAT3 signaling pathway, ATL I has also been demonstrated to decrease cell viability, induce apoptosis, and impede cell migration in human melanoma cells A375, as well as down-regulate the levels of STAT3 target genes Bcl-xL, MMP-2, and MMP-9." (PMID 37241729, 2023). "Thus, we sought to determine the site of STAT3 phosphorylation that mediates melanoma cell sensitivity to sunitinib." (PMID 36720918, 2023). "On the contrary to melanoma cells, this study showed that increased STAT3 phosphorylation by FNDC3B silencing could play a role in suppressing cell migration, invasion, and stemness in GBM cells." (PMID 38137388, 2023). "Moreover, apigenin treatment suppressed melanoma metastasis to the lungs in C57BL/6 mice and inhibited the phosphorylation of STAT3 in melanoma cells." (PMID 36675015, 2023). "Melanoma cell growth and development are stimulated by aberrant STAT3 expression." (PMID 36852795, 2023). "In some cases, eEF2K may upregulate the levels of STAT3, as observed in various cell types, including melanoma." (PMID 37875468, 2023). "As such, STAT3 has been identified as a contributor to the anoikis resistant phenotype in melanoma." (PMID 37181747, 2023). "Indeed, literature data suggest a crucial role of the aberrant, hyperactivated STAT3 pathway in driving drug resistance to vemurafenib in melanoma cells." (PMID 36979673, 2023). "However, by employing multiple melanoma cell lines, we detected a heterogenous pattern of STAT3 activation in microglia cells exposed to signals from different melanoma cell lines." (PMID 37296634, 2023). "Furthermore, a STAT3-specific inhibitor, BP-1-102, is able to decrease the expression of PD-L1 in a dose-dependent manner in melanoma cells." (PMID 37444518, 2023). "We next set to identify melanoma-derived factors that may induce STAT3 phosphorylation and SOCS3 upregulation in microglia." (PMID 37296634, 2023). "Moreover, c-Src/FAK/STAT3 signalling regulates the expression of E-cadherin, controlling the migratory capability of melanoma cells." (PMID 37896150, 2023).
melanoma (continued). "Complementary studies in control and HLA-G-depleted parental lung and melanoma BMICs showed that HLA-G ablation resulted in reduced p-STAT3 levels in lung and melanoma BMICs when compared to their control counterparts, demonstrating a bona fide role for HLA-G in STAT3 signaling activation in BMICs." (PMID 36780531, 2023). "Moreover, TQ treatment has been found to induce apoptosis of B16-F10 melanoma cells and antitumor activity in a murine model of intracerebral melanoma through the inhibition of STAT3 phosphorylation." (PMID 37375831, 2023). "Constitutive activation of STAT3 plays a vital role in the development of melanoma." (PMID 36674794, 2023). "HPF can block STAT3 tyrosine phosphorylation in all the BRAF-mutated melanoma cell lines after 24 h treatment without affecting the total STAT3 protein level." (PMID 36674794, 2023). "The authors revealed for the first time that KIF22 depletion could restrain proliferation, glycolysis and accelerate apoptosis of melanoma cells by inactivating EGFR/STAT3 signaling." (PMID 37944197, 2023). "Indeed, other authors reported that the STAT3 pathway is activated in response to stimulation of the heterodimeric GP130/IL-6 cytokine-specific receptor complex in melanoma cells." (PMID 36979673, 2023). "STAT3 activation can prevent apoptosis and support the proliferation of melanoma cells." (PMID 37595251, 2023). "Hypoxia-induced autophagy in melanoma cells leads to STAT3-mediated suppression of the tumor-lysing function of cytotoxic T cells, while inhibiting melanoma autophagy restores CTLs’ function through ubiquitin proteasome system and SQSTM1/p62 involved down-regulation of phospho-STAT3." (PMID 36003368, 2022). "Moreover, brusatol also showed anti-cancer activity in head and neck squamous cell carcinoma, melanoma and laryngeal cancer through inhibiting STAT3 and the Nrf2 signaling pathways and abrogating JAK2/STAT3 signaling-mediated EMT process, respectively." (PMID 35370639, 2022). "In this study, we found that EEF2K might play a role in the regulation of melanoma progression through the p‐STAT3/SPP1 pathway." (PMID 35184394, 2022). "In addition, it inhibited melanoma cell proliferation and strongly induced melanoma cell death by inhibiting the phosphorylation and activation of the Src protein and the activation of downstream signals (e.g., STAT3 protein)." (PMID 35684449, 2022). "Another preclinical study revealed that this agent lowers the growth of melanoma cell lines and induces mitochondrial apoptosis, which impairs cell migration and invasion, reduces expression of phosphorylated STAT3 at Tyr705, and inhibits matrix metalloproteinase-2 and -9 expression." (PMID 36678712, 2022). "EEF2K mediates melanoma progression through p‐STAT3/SPP1 axis." (PMID 35184394, 2022). "Moreover, co‐immunoprecipitation assay demonstrated that endogenous EEF2K was precipitated with endogenous STAT3, but not with PKM2, suggesting that EEF2K promotes the phosphorylation of STAT3 in a PKM2‐independent manner in melanoma cells." (PMID 35184394, 2022). "For example, the EAHM formula composed of only Sophorae Flos and Lonicerae Japonicae Flos, the high-frequency materials in this study, reprograms the immune microenvironment and exhibits anti-melanoma effects based on the mechanism that inhibits STAT3 signaling in B16F10 melanoma-bearing mice." (PMID 35745164, 2022). "Here, we identified that EEF2K/p‐STAT3/SPP1 may be a novel oncogenic pathway in melanoma progression and could be a potential target for a novel combinational therapy for melanoma." (PMID 35184394, 2022). "A recently conducted study has shown that the ratio of phosphorylated STAT1 to STAT3 may be a biomarker that can predict the progression of melanoma." (PMID 35401182, 2022). "So, we speculated that the potential mechanism of malignant phenotypes suppressed by apatinib combined with WZB117 in melanoma cells might be related to the inhibition of glycolysis through the STAT3/PKM2 signaling pathway." (PMID 36188586, 2022).